KRAS (KRas proto-oncogene, GTPase)
Diseases named in the same sentence as KRAS in open-access papers (continued):
Sharing a sentence is not in itself a finding about the gene and the disease.
cancer (continued). "KRAS oncogenes harboring codon G12 and G13 substitutions are considered gatekeeper mutations which drive oncogenesis in many cancers." (PMID 33959410, 2021). "KRAS oncoprotein is commonly mutated in human cancer, but effective therapies specifically targeting KRAS‐driven tumors remain elusive." (PMID 34369083, 2021). "Salirasib, the Ras inhibitor, has been used to investigate the potential molecular targets of various compounds in cancer, especially those with KRAS mutation." (PMID 34837922, 2021). "The problem of finding an effective inhibitor is related to the variety of mechanisms present in cancer cells with KRAS mutation." (PMID 34572931, 2021). "In mutant KRas-driven cancer cells, the “open conformation” dominantly results from the activated KRas due to the “open conformation” accounting for more partition in mutated KRas than in wild-type HRas and NRas." (PMID 35069209, 2021). "Though preventing RAS from membrane association was the right approach, inhibiting farnesylation allowed for NRAS and KRAS mutant cancers to initiate alternative membrane association mechanisms, such as geranylgeranylation, another form of prenylation." (PMID 34830283, 2021). "Nevertheless, it has been demonstrated that the resistance of KRAS-mutated cancers to the induction of apoptosis by exogenous TRAIL can be overcome by inhibiting the endogenous TRAIL." (PMID 33791337, 2021). "KRAS mutations influence the stellate cells/pluripotent stem cells of the pancreas (activated stellate cells are referred to as cancer-associated fibroblasts or CAF)." (PMID 34638560, 2021). "In many Kirsten rat sarcoma viral oncogene homolog (KRAS) mutated oncogenic cancers, ROS play an important role in anchorage-independent growth through regulation of the ERK MAPK signaling pathway." (PMID 33435480, 2021). "A recent study demonstrated that stimulating KRAS-driven LUAD cancer metastasis was induced by KEAP1 loss but NRF2 activation." (PMID 34226519, 2021). "Small GTPase KRAS is one of the most frequently mutated oncogenes and is mutated in more than 30% of human cancers." (PMID 33917906, 2021). "TBK1 regulates an autocrine CCL5 and IL-6 signaling, inducing carcinogenesis in KRAS mutated cancer." (PMID 33777798, 2021). "MEK-induced drug resistance was attenuated in both G12 and G13 variants, which account for 80% of all KRAS-dependent cancers." (PMID 34946644, 2021). "Mutant KRAS is a known driver mutation for cancer development and progression, making KRAS mutant proteins good candidates for therapeutic development." (PMID 34822010, 2021). "KRAS is a frequently mutated gene in different cancers, and activating mutations in KRAS are observed in 20% of human tumors, including NSCLC." (PMID 33740988, 2021). "Analysis of genomic data from 55,308 cancers showed a significant trend toward co-occurrence of mutations in KRAS and SMAD4." (PMID 35008475, 2021). "GLUT1 is one of the most important enzymes upregulated in CRC and is associated with the KRAS mutation which enhances glucose absorption by cancer cells." (PMID 34571724, 2021). "Activation of the proto-oncogene KRAS mutation pathway is common in cancer cells and it is responsible for promoting apoptosis inhibition, migration and proliferation in many cancer cells." (PMID 34044804, 2021). "The anticancer activity of LXH-254 is demonstrated in tumors carrying BRAF/RAS co-mutations, but it has moderate activity against cancers driven by KRAS mutants." (PMID 34607583, 2021). "The RAS family of oncogenes (HRAS, NRAS, and KRAS) are among the most frequently mutated protein families in cancers." (PMID 33924994, 2021). "We compared the most common hotspot mutations in KRAS between CUP, and other KRAS mutation enriched cancer types." (PMID 34302033, 2021).
cancer (continued). "Mutations of the proto-oncogene KRAS are the most frequent gain-of-function alterations found in cancer." (PMID 33777798, 2021). "On the basis of these findings, multiple strategies using VS-6766/CH5126766 alone (NCT03681483) or with other agents such as defactinib (NCT03875820, NCT04625270, NCT04620330) are currently under clinical investigation in cancers with KRAS mutations." (PMID 34946644, 2021). "The last 30 years of research have led to significant discoveries and improvements in cancer treatment, but new therapeutic approaches are still needed, especially for cancers with KRAS mutations." (PMID 34208655, 2021). "Oncogenic KRAS plays important roles in the metabolic rewiring of cancer cells, and has been implicated in the decoupling of glycolysis and TCA metabolism." (PMID 34233735, 2021). "Fourth, the findings showing IGF2BP1 overexpression promoted colony formation and chemoresistance were obtained in two CRC cell lines carrying a KRAS G13D mutation according to the Catalogue of Somatic Mutations In Cancer (COSMIC)." (PMID 34203267, 2021). "Suppression of the expression of mutated KRAS by antisense or siRNA caused cell cycle arrest and apoptosis in KRAS-mutated cultured cancer cell lines, and epithelial-mesenchymal transition (EMT) was closely associated with KRAS dependency." (PMID 33793658, 2021). "Wild-type KRAS (KRASWT) amplification has been shown to be a secondary means of KRAS activation in cancer and associated with poor survival." (PMID 33795683, 2021). "The Ras protein family includes three subtypes (KRAS, HRAS, and NRAS), and 85% of Ras-driven cancers are caused by KRAS mutations." (PMID 34257597, 2021). "KRAS is one of the most mutated proto-oncogene in human cancers, and is highly mutated in a variety of cancers, including pancreatic ductal adenocarcinomas (PDAC), lung cancer, and colorectal cancer." (PMID 33000412, 2021). "In this sense, BEAMing (Beads, Emulsions, Amplification, and Magnetics) represents a highly sensitive dPCR method for identifying and quantifying hotspot variants in cancer-related genes of cfDNA, such as KRAS and NRAS." (PMID 34640513, 2021). "In cancer cells harbouring KRAS G12C mutations, SHP2 inhibition triggers a senescence response in vivo and in growth factor-limited conditions." (PMID 34064232, 2021). "Via DR5 activation, TRAIL stimulates the migration and invasion of KRAS-mutated cancer cells in a Rac1-dependent manner." (PMID 33257838, 2021). "A549.R2 cells showed a reduced expression of genes defining KRAS dependency (gene set M2851) or related to overexpression of oncogenic KRAS (gene set M2892) compared to the parental A549 cancer cells (KRAS mutation p.G12S c.34G>A)." (PMID 35582010, 2021). "In contrast, our integrated genomic-epidemiology approach provides a revised estimate of 15% of cancers harboring a KRAS, NRAS, or HRAS mutation – less than half of those previously reported estimates." (PMID 34645806, 2021). "Several cancer-associated genes, such as KRAS and PIK3CA, are frequently mutated in the endometriotic epithelium." (PMID 34202354, 2021). "We evaluated the effect of miR-193a-3p in KRAS-mutant cancer cells by using gain-and-loss-of-function experiments." (PMID 34299137, 2021). "The clinical observation that KRAS mutations differ in position and type of substitution according to cancer type is an intriguing, and yet unexplained phenomenon." (PMID 33632153, 2021). "A clinical trial of VS-6766, a dual RAF–MEK inhibitor, has reported early single agent activity in non-G12C mutated KRAS driven cancers." (PMID 33859342, 2021).
cancer (continued). "KRAS is implicated in a plethora of essential pathways implicated in cancer cells proliferation, angiogenesis, invasion, and dissemination." (PMID 34199293, 2021). "The KRAS oncogene is mutated in approximately ~30% of human cancers, and the targeting of KRAS has long been highlighted in many studies." (PMID 33917906, 2021). "The KRAS gene is often mutated at several hotspot codons in cancer, resulting in similar, yet distinct, functional impacts on the KRAS protein." (PMID 33753749, 2021). "KRAS is overwhelmingly the most commonly mutated RAS isoform in cancer, comprising 85% of oncogenic RAS mutations." (PMID 33466360, 2021). "As a hallmark oncogene, KRAS upregulates glycolysis-related enzymes and promotes energy supply in cancer cells, indicating a worse survival." (PMID 34447748, 2021). "Testing for activating KRAS mutations has important implications for diagnosis and the personalized medicine of cancers." (PMID 33467412, 2021). "For example, KRAS is mutated in ~25% of all human cancers, which produces a constitutively active form of the protein that impairs mitochondrial function and induces glucose-dependency in transformed cells." (PMID 33742081, 2021). "Our data confirm that PKM2 and its direct substrate, c-Myc, are major players of KRAS mutation induced cancer by performing various metabolic (i.e., positive effect on GLUT1) and non-metabolic (i.e., up-regulation of autophagy) functions." (PMID 33925206, 2021). "The epidermal growth factor receptor (EGFR) upstream of KRAS is also frequently mutated in various cancers and has also been sought as a therapeutic strategy to tackle KRAS mutant cancers." (PMID 33801965, 2021). "In cancers with KRAS mutations, RSF1 overexpression can increase the sensitivity of KRAS mutation-driven cancers to cytotoxic drugs." (PMID 34147108, 2021). "For example, for an initial quick screen of cancer clones, our study quantified mutant KRAS alleles by pyrosequencing and then confirmed the origin of iPSCs by comparative genome hybridization (CGH)." (PMID 33202305, 2020). "In summary, the KrasP34R and KrasT58I mouse strains described here provide what we believe to be new in vivo models for elucidating how germline and somatic KRAS mutations perturb cell fate decisions and contribute to human developmental disorders and cancer." (PMID 32990679, 2020). "In summary, six diarylpentanoids were synthesized and investigated for their anti-cancer potential against a panel of KRAS- and BRAF-mutated CRC cell lines." (PMID 32858795, 2020). "A high percentage of human cancers harbor a gain‐in‐function mutation in RAS that results in the constitutive activation of either the KRAS, NRAS, or HRAS isozymes, which drive multiple aspects of malignant transformation and progression." (PMID 33073260, 2020). "As an attractive immunotherapy, cancer vaccines can overcome binding difficulties of small molecules; however, the weak immunogenicity and production difficulties of reported KRAS mutation vaccines limit their clinical application." (PMID 32903495, 2020). "For cancer patients with known KRAS or PIK3CA mutations (as determined by tissue testing) we also compared the presence of oncogenic mutations in plasma and urine samples." (PMID 32251424, 2020). "For instance, oncogenic Ki-ras2 Kirsten rat sarcoma viral oncogene homolog (KRAS) mutations are present in about 30% of all human cancers." (PMID 32397368, 2020). "It has been shown that mutated KRAS not only plays pivotal roles in cancer initiation, but also contribute to several hallmarks of human cancer." (PMID 33122197, 2020).
cancer (continued). "Overall, the results of this study will facilitate development of new effective drugs for the inhibition of KRAS mutations in patients with cancer." (PMID 32486141, 2020). "The frequencies of KRAS variant alleles appears cancer type specific, reflecting the various carcinogenic processes." (PMID 32725342, 2020). "Our data indicate that KRAS prenylation and the expression of related enzymes are associated with a higher susceptibility to initiate cancer." (PMID 32887255, 2020). "The limit of detection (LOD) for detecting KRAS mutation was differently reported depending on the sample types; 0.05% for G12D and 0.01% for G12C using cancer cell lines with TaqMan MGB probes; 0.2% using FFPE CRAC samples with KRAS multiplex kit." (PMID 32708359, 2020). "In non recto-sigmoid cancers, high cholesterol was associated with KRAS WT (OR 0.39, CI 0.15–0.97, p = 0.04)." (PMID 32594310, 2020). "With an incidence rate of up to 22% in solid tumor malignancies, KRAS is one of the most prevalent oncogenic driver mutations in cancer." (PMID 32560187, 2020). "Considering the association between TERT expression and KRAS mutation, therapeutic drugs targeting this pathway can be developed for cancer prevention." (PMID 32932803, 2020). "Numerous studies indicated that KRAS mutations serve as prognostic and predictive biomarkers in multiple types of cancer, as it can provide information for patients’ survival outcomes and suggestions on the use of EGFR-inhibitors." (PMID 33254149, 2020). "The KRAS mutations most commonly known to promote cancer are in a 4–5 base pair sequence of DNA in codons 12 and 13 of the gene." (PMID 32059456, 2020). "Based on the well-validated role of mutation- induced activation of KRAS in driving cancer development and growth, comprehensive efforts have been undertaken to develop therapeutic strategies to halt mutant KRAS function for cancer treatment." (PMID 32308773, 2020). "In KRAS WT patients, the death rate caused by cancer and other reasons were 42.59% and 14.83%, respectively." (PMID 32547859, 2020). "In both univariable and multivariable analysis, there was a statistically significant association between chol:HDL ratio and KRAS mutation in recto-sigmoid cancers (p = 0.02)." (PMID 32594310, 2020). "KRAS has been a target for drug design for more than 30 years because it is the most commonly mutated oncogene in human cancers, including pancreatic (90%), colon (40%), and non-small cell lung cancers (20%)." (PMID 32486141, 2020). "In cancer cells, KRAS mutation induces transcription of genes encoding key enzymes of anabolic glucose metabolism, including glucose transporter 1, hexokinases, phosphofructokinase 1, and lactate dehydrogenase A." (PMID 32481524, 2020). "For example, it has been reported that mutations of KRAS at codon 12 have greater transforming ability than at codon 13 and are linked with a more aggressive cancer phenotype, although, patients with codon 13 mutations exhibit a markedly worse prognosis." (PMID 32300895, 2020). "In human cancers, KRAS mutation is considered to be one of the most common driver mutation in the lung, colorectal and pancreatic carcinogeneses." (PMID 32370075, 2020). "Here, we focused on the identification of a low-toxicity treatment consisting of the combination of FMD cycles with pharmacological dosages of vitamin C for the treatment of KRAS mutated cancers." (PMID 32393788, 2020). "Kirsten-RAS (KRAS) has been the target of drugs because it is the most mutated gene in human cancers." (PMID 32486141, 2020). "The RAS family consists of KRAS, NRAS, and HRAS; among them, KRAS mutation is one of the most common molecular events, seen in 17–25% of human cancers." (PMID 32695666, 2020). "Most mutations affect the KRAS isoform (~86%), where the frequency and distribution vary depending on the cancer type." (PMID 33116132, 2020).
cancer (continued). "KRAS is the most commonly mutated oncogene in human cancer, and its mutation is generally associated with resistance to treatment and poor survival." (PMID 33127935, 2020). "scRNA-seq additionally revealed that this sample contained cancer cells harboring KRAS G13D and KRAS G12C occult mutations." (PMID 32822576, 2020). "Overall, the results presented herein will facilitate development of novel drugs for inhibition of KRAS mutations in cancer patients." (PMID 32486141, 2020). "KRAS is the most frequently mutated proto-oncogene in cancer cells, and its pharmacological targeting has remained challenging in cancer therapy." (PMID 33117331, 2020). "The three RAS oncogenes, NRAS, HRAS, and KRAS, make up the most frequently mutated gene family in human cancers." (PMID 32308773, 2020). "The ability to inhibit the oncogenic KRAS has been the holy grail of cancer research and the search for inhibitors is immensely ongoing as KRAS-mutated tumors are among the most aggressive and refractory to treatment." (PMID 32560574, 2020). "Combining next generation sequencing (NGS) with the genome-editing approach would be a promising strategy for targeting KRAS or other oncogenic mutations for personalized cancer treatment." (PMID 32308773, 2020). "Here we performed a SEER based study to evaluate the association between KRAS mutation status and the cancer specific survival (CSS) of CRC patients by using competing risk analyses." (PMID 32547859, 2020). "In KRAS MT patients, the death rate caused by cancer and other reasons were 49.89% and 13.69%, respectively." (PMID 32547859, 2020). "This was also attached to their compound MRTX849 which is now in phase I/II clinical trial in treatment of cancers with KRAS-G12C mutation." (PMID 32770300, 2020). "Oncogenic KRAS mutations are the most frequent mutations in human cancer, but most difficult to target." (PMID 33116132, 2020). "This is a unique finding for FGFR1 and RGNT, as there is not typically selection pressure for loss of the remaining wildtype allele for other mutated oncogenes in human cancers of any other type (e.g. KRAS, BRAF, EGFR)." (PMID 32859279, 2020). "Yet, clinical trials testing immune checkpoint blockade in KRAS-mutated cancers have yielded disappointing results suggesting other, additional means endow these tumors with the capacity to escape immune recognition." (PMID 32194994, 2020). "The most commonly used methods of detection for cancer mutations, PCR and sequencing, have suboptimal sensitivity in case of KRAS diagnostics." (PMID 36703315, 2020). "It will be also important that future research investigate other specific aspects of KRAS mutations-induced cancers." (PMID 32244355, 2020). "Another frequently mutated gene in human cancers is KRAS, whose activation leads to deregulated proliferation." (PMID 32932943, 2020). "The present study has successfully established a non‐invasive diagnostic method for KRAS mutation detection in circulating DNA of cancer patients." (PMID 32207862, 2020). "The results revealed a statistically significant association between KRAS status according to primary cancer location and each of chol:HDL ratio and serum cholesterol." (PMID 32594310, 2020). "AMG 510 is the first small molecule inhibitor to successfully target KRAS mutation in advanced cancer patients, according to findings presented at the 2019 American Society of Clinical Oncology Annual Meeting." (PMID 32351019, 2020).